ABCC9 (ATP binding cassette subfamily C member 9)
Diseases named in the same sentence as ABCC9 in open-access papers (continued):
Sharing a sentence is not in itself a finding about the gene and the disease.
type 2 diabetes mellitus (1 paper, 2023). A type of diabetes mellitus that is characterized by insulin resistance or desensitization and increased blood glucose levels. "Despite the absence of monoclonal antibodies against known type-2 diabetes small molecule targets ABCC8, ABCC9, DPP4, and KCNJ11, these genes demonstrated AB tractability estimates greater than 60%, along with interleukin receptors IL4R and IL17RA." (PMID 37225853, 2023).
ventricular fibrillation (1 paper, 2022). A disorder characterized by an electrocardiographic finding of a rapid grossly irregular ventricular rhythm with marked variability in QRS cycle length, morphology, and amplitude. "Due to abnormal KATP function, patients with ABCC9 mutations are often reported to have a low potassium serum level which, by itself, can be a severe provocative factor for triggering ventricular fibrillation." (PMID 35495129, 2022).
cancer (9 papers, 2017 to 2025). A tumor composed of atypical neoplastic, often pleomorphic cells that invade other tissues. "ABCC9 has been linked to drug resistance in cancer, while MIR311 and MIR409 are thought to regulate gene expression via hypomethylation, thereby promoting cancer progression." (PMID 39649173, 2024). "This review will further explore the varied expression changes in ABCC8 and ABCC9 in a range of cancers, highlighting their potential impact on cancer behavior and treatment responses." (PMID 38396807, 2024). "Our data also support the safe use of zoledronic acid as a KATP channel blocker in the treatment of macroadenoma in C.S. associated with G.O.F. mutations of the ABCC9 and KCNJ8 genes or in cancers in which these subunits were associated with poor prognosis." (PMID 37180726, 2023). "The AOD value showed that the expression of ABCC9 protein in malignant tumors was significantly lower than that in para-cancer tissues and benign tumors (P < 0.05)." (PMID 35071399, 2021). "This study revealed that the KCNJ8, KCNJ11, ABCC8, ABCC9 genes are downregulated in cancer of the female reproductive tract when compared with the correspondent normal tissues." (PMID 32457608, 2020). "To precisely identify the molecular mechanisms underlying TRIM11-induced ABCC9 expression in NPC, we performed luciferase reporter assays to assess the effect of TRIM11 on important cancer pathway." (PMID 32382014, 2020). "KCNJ11, KCNJ8, and ABCC9 genes are upregulated in cancers but ABCC8 is downregulated." (PMID 37180726, 2023). "The expression of adjacent gene ABCC9 was significantly decreased in the malignant tumor group." (PMID 35071399, 2021). "In the future, additional studies on the regulation of ABCC9 protein in cancer cells are needed." (PMID 35071399, 2021). "In addition, many studies have shown that ABCC9 can be used as a biomarker for cancers." (PMID 35071399, 2021). "However, the number of ABCC9 positive cells was significant decreased in malignant tumors." (PMID 35071399, 2021). "Research has demonstrated varying expression patterns of the ABCC8 and ABCC9 genes, crucial in forming KATP channels, across different cancer types." (PMID 38396807, 2024). "The minoxidil-induced overactivation of Kir6.1/2-Sur2A/B subunits in rats provoked a cancer reaction similar to what was observed in some cases of C.S. Omics data reporting the upregulation of the ABCC9, KCNJ11, and KCNJ8 genes in cancers support these conclusions." (PMID 37180726, 2023). "Also, pharmacovigilance data were analyzed to assess the correlation of ABBC8, ABCC9, KCNJ11, and KCNJ8 genes with cancer reactions induced by drugs targeting the different KATP channel subunits." (PMID 37180726, 2023). "The methylation results of ABCC9 promoter CpG island revealed that high levels of methylation occurred at multiple sites in cancer tissues, but no new methylation sites were formed." (PMID 35071399, 2021). "Furthermore, a negative correlation was observed between ABCC9 expression and cancer grading, with positive cells basically disappearing in cancer samples of grade III." (PMID 35071399, 2021).
tumor (9 papers, 2018 to 2025). "Total of 6 tumor sample with ABCC9 mRNA levels significantly reduced were tested by methylation analysis." (PMID 35071399, 2021). "In addition, ABCC9 protein expression and mRNA levels were significantly reduced in tumor samples with ABCC9tetra locus instability (P < 0.05)." (PMID 35071399, 2021). "Pericyte-1 was enriched in the tumor fraction and characterized by higher expression of genes related to a pro-inflammatory capillary phenotype (RGS5, KCNJ8, AXL, ABCC9, PDGFRB, and THY1)." (PMID 36180422, 2022). "Through the HPA database, we found that three genes (ABCC9, AHNAK, and DIP2C) had low expression in patients with tumours, whereas eight genes (PLOD1, SLC3A2, RUNX2, RAD9A, CHMP4C, DARS2, CLIC3, and POU5F1) were highly expressed." (PMID 36685927, 2022). "In the tumor sample of grade III, ABCC9 strongly positive cells almost disappeared, and were only weakly or micro-expressed in cells." (PMID 35071399, 2021). "The most altered ABC transporter gene in any PDAC subtype was ABCC9; found altered in 21% of all in QM-PDAC tumours." (PMID 30018740, 2018). "Human tumor transcriptomic data for 377 HCC patients also show a positive correlation of multiple ABC transporters including the ABCB1, ABCC3, ABCC9 and ABCG2 with GHR expression, while ABCC1,ABCC4 and ABCG1 levels correlated with IGF1R expression, confirming our in vivo observations." (PMID 35865483, 2022). "While three genes (AHNAK, ABCC9, and DIP2C) were highly expressed in normal tissues, eight genes (CHMP4C, CLIC3, DARS2, PLOD1, POU5F1, RAD9A, RUNX2, SLC3A2) were highly expressed in tumour tissues." (PMID 36685927, 2022). "Eight genes (SLC3A2, DARS2, DIP2C, PLOD1, RUNX2, ABCC9, AHNAK, and CLIC3) may be involved in the malignant transformation of tumours, and three genes (CHMP4C, POU5F1, and RAD9A) may have a protective effect in patients with tumours." (PMID 36685927, 2022). "Through the HPA database, we found that three genes, namely ABCC9, AHNAK, and DIP2C, had low expression in patients with tumours, and eight other genes—PLOD1, SLC3A2, RUNX2, RAD9A, CHMP4C, DARS2, CLIC3, and POU5F1—were highly expressed in patients with tumours." (PMID 36685927, 2022).
genetic disorder (3 papers, 2016 to 2025). "Cantú syndrome (CS) is a rare genetic disorder caused by gain-of-function (GOF) mutations in the KCNJ8 (Kir6.1) or ABCC9 (SUR2) subunits of ATP-sensitive potassium (KATP) channels." (PMID 41020224, 2025). "Genetic variants in the ABCC9 gene, encoding the SUR2 auxiliary subunit from KATP channels, were previously linked with various inherited diseases." (PMID 35495129, 2022).
neurodegenerative disease (2 papers, 2020). A disorder of the central nervous system characterized by gradual and progressive loss of neural tissue and neurologic function. "These enriched TFs displayed maximum interactions with their target genes (GPR50, ABCC9, ZNF667 and CALB1) and could prove relevant to several neurodegenerative diseases." (PMID 32967368, 2020).
benign tumors (1 paper, 2021). "Immunohistochemistry reflected that ABCC9 was overexpressed in both normal and paracancerous tissues and in benign tumors, indicating that it is involved in the assembly of the KATP channel in the breast." (PMID 35071399, 2021).
heart diseases (1 paper, 2024). "This evidence suggests that both gain-of-function (GOF) and LOF mutations in ABCC9 can lead to diverse cardiac abnormalities, from Cantu syndrome to Brugada syndrome, emphasizing the complex role of KATP channels in heart diseases." (PMID 39337275, 2024). "Moreover, a recent case highlighted a loss-of-function (LOF) variant in ABCC9 associated with severe ventricular arrhythmias and DCM, further validating the significant role of this gene in cardiac electrophysiology and its impact on cardiac disease phenotypes." (PMID 39337275, 2024).
infection (1 paper, 2024). The state of being infected such as from the introduction of a foreign agent such as serum, vaccine, antigenic substance or organism. "A striking exception is that Kcnj8 and Abcc9 expression is strongly upregulated in liver macrophages after 8-48 h infection with C. Albicans." (PMID 39669557, 2024). "Because Kcnj8 and Abcc9 expression matches those cells that have developed or innate functions to rapidly respond to infections or immune stressors, KATP channels may have a role in responses to these stressors." (PMID 39669557, 2024). "Functions of Kcnj8 and Abcc9 need to be explored in NKT cells, NK cells, and macrophages and CD8+ T cells following infection." (PMID 39669557, 2024).
ABCC9 also shares sentences with these, for which no sentence is quoted: Brugada syndrome (3 papers); cardiac arrhythmia (3); hypertrichotic osteochondrodysplasia (3); Macrocephaly (3); developmental delay (2); early repolarization syndrome (2); Holt-Oram syndrome (2); hypertension (2); mastitis (2); Obesity (2); osteochondrodysplasia (2); ovarian cancer (2); periventricular leukomalacia (2); Ventricular arrhythmia (2); age (1); Alzheimer disease (1); Anxiety (1); asthma (1); autoimmune disease (1); Barth syndrome (1); biliary tract cancer (1); Char syndrome (1); Coffin-Lowry syndrome (1); Cornelia de Lange syndrome (1); COVID-19 (1); Danon disease (1); dementia (1); diabetic nephropathy (1); DiGeorge syndrome (1); endothelial dysfunction (1).
A further 30 diseases each share a sentence with ABCC9 in 1 paper.